RNU6-945P (RNA, U6 small nuclear 945, pseudogene)
Gene: Small nuclear RNA gene on chromosome 19 (40,299,478 to 40,299,584, reverse strand). Ensembl gene ENSG00000206674.
Homologues: Orthologues: chimpanzee U6 (99% identical), macaque U6 (92% identical). Paralogues in human: RNU6-1181P (91% identical), RNU6-12P (90% identical), RNU6-13P (90% identical), RNU6-16P (90% identical), RNU6-32P (90% identical), RNU6-1 (89% identical), RNU6-1145P (89% identical), RNU6-1241P (89% identical), RNU6-1316P (89% identical), RNU6-17P (89% identical), RNU6-18P (89% identical), RNU6-19P (89% identical), and 1289 more.